CD44 (CD44 molecule (IN blood group))
Diseases named in the same sentence as CD44 in open-access papers (continued):
Sharing a sentence is not in itself a finding about the gene and the disease.
myocardial infarction (13 papers, 2015 to 2025). Gross necrosis of the myocardium, as a result of interruption of the blood supply to the area, as in coronary thrombosis. "Third, CD44 is predicted to be one of the key genes underlying the pathophysiological association between plaque instability and myocardial infarction progression." (PMID 37684253, 2023). "Studies in CD44-deficient mice that underwent myocardial infarction showed prolonged inflammation, reduced collagen deposition in scars, decreased myofibroblast infiltration, and decreased TGF-β signaling." (PMID 34335086, 2021). "The CD44 signaling pathway is crucial for post-myocardial infarction healing by modulating inflammation and fibrosis." (PMID 41393293, 2025). "Modulating inflammation is vital for healing, with microRNAs like miR-19a/b and miR-20a aiding keratinocyte response, and the CD44 pathway enhancing recovery post-myocardial infarction by regulating inflammation and fibrosis." (PMID 41393293, 2025). "A CD44 knockout - study in myocardial infarction model showed the important role of CD44+ EVs in angiogenesis." (PMID 37662913, 2023). "In this study, we used CD44 knockout mice to study the in vivo impacts of CD44 on ischemic angiogenesis in myocardial infarction." (PMID 36463112, 2022). "In conditions after myocardial infarction, CD44 and RHAMM help in wound healing by reorganization of the extracellular matrix and collagen deposition." (PMID 34335086, 2021). "Our findings are supported by a report that CD44-positive MSCs served as a major precursor pool for fibroblasts that mediate scar formation and wound healing after myocardial infarction." (PMID 30809271, 2019). "It has been previously reported that endogenous CD44-positive MSCs contribute to the fibroblast population in myocardial infarction." (PMID 30809271, 2019). "The aim of this study was to evaluate the effects of four weeks long consumption of white wine to the expression of granulocyte and monocyte inflammatory markers (CD15s, CD11b and CD44), 24h after the surgically inflicted myocardial infarction." (PMID 29746525, 2018). "Neutrophils and monocytes through their CD15s, CD11b and CD44 adhesion molecules are implicated in the initiation and resolution of cardiac inflammation as well as in healing processes after the myocardial infarction (MI)." (PMID 29746525, 2018). "The defect of the CD44 signal cascade may play an essential role in the pathogenesis of adverse remodeling after myocardial infarction." (PMID 35370712, 2022). "In addition, CD44, hyaluronan, and their interactions are indispensable in developing myocardial fibrosis and cardiac remodeling after myocardial infarction, accelerating the progress of heart failure." (PMID 35370712, 2022). "Therefore, we performed a four weeks consumption trial with white wine evaluating the effects on granulocyte and monocyte inflammatory markers (CD15s, CD11b and CD44), during inflammatory phase following experimental myocardial infarction in rats." (PMID 29746525, 2018). "Furthermore, it suggests that CD44 may promote the conversion of macrophages to foam cells within lesions, leading to increased lesional lipid accumulation and immune cell content, conditions that favor lesion rupture, a risk factor for heart attack and stroke." (PMID 26029216, 2015). "Our studies elucidate that CD44 plays a key role in plasma exosomal miRNA-enhanced angiogenic FGFR2 singling transduction and ischemic angiogenesis in the early stage of myocardial infarction." (PMID 36463112, 2022). "CD44 facilitates the healing response, by promoting fibroblast infiltration, proliferation, myofibroblast differentiation, and ECM deposition and remodeling following myocardial infarction." (PMID 26029216, 2015).
type 2 diabetes (13 papers, 2010 to 2024). "The CD44 gene has been linked to the molecular pathogenesis of Type 2 diabetes in humans and its role in metabolism has been recently reviewed." (PMID 37383542, 2023). "In a genome-wide association study, CD44 was found to be a functionally associated gene in type 2 diabetes patients." (PMID 25954275, 2015). "An acquired CD44 phenotype in macrophages was associated with type 2 diabetes and NAFLD-HCC." (PMID 34408183, 2021). "The same study found that intraperitoneal administration of an anti-CD44 antibody in a murine model of high fat diet induced type 2 diabetes, decreased blood glucose levels, and macrophage infiltration in adipose tissues." (PMID 25954275, 2015). "In a small network, known causal components ADA and CD26 (DPP4) form a cascade with the predicted causal component CD44 (green node) connected by RANTES (CCL5) (blue node), which harbors promoter polymorphisms associated with type 2 diabetes." (PMID 20815942, 2010). "Because CD44 functions as a receptor, it might provide a convenient therapeutic target in the management of type 2 diabetes." (PMID 23505504, 2013). "Notably, BCAT2, CD44 and HIF1A were directly related to the pathway of maturity onset diabetes of the young." (PMID 37904700, 2023). "Nine genes not previously reported to be associated with type 2 diabetes were significantly dysregulated in our organ donor and PPP cohorts (ANKRD23/39, ASCL2, HHATL, NSG1, PCDH20, SCTR, CD44, FAM102B and FBXO32)." (PMID 29185012, 2018). "PAK3, CD44, CD5, SOCS3, VAV1, and PIK3CD are negatively correlated with cardiac systolic function, and P2RY1 is positively correlated with LVEF, which may be referred to in studies on type 2 diabetes." (PMID 34925642, 2021). "Hence, the positive correlation of CD44 and OPN with the altered HOMA was not assessed, but we can confirm that none of the patients recruited in this study had known type 2 diabetes." (PMID 33047155, 2020).
urothelial carcinoma (13 papers, 2015 to 2025). A malignant neoplasm derived from the transitional epithelium of the urinary tract (urinary bladder, ureter, urethra, or renal pelvis). "We evaluated the expression of basal markers (cytokeratin (Ck) 5, p63), luminal markers (Ck8, Ck20), a tumor initiating marker (CD44), a proliferating marker (Ki67), and urothelial carcinoma markers (GATA3, uroplakin II (UPKII)." (PMID 39921252, 2025). "Among a consecutive series of pT2 urothelial carcinoma patients, our system identified four molecular subtypes using CD44, CK5/6, CK20, and pPARγ." (PMID 35805028, 2022). "Analyses using immunofluorescence and fluorescence-activated cell technology confirmed that CD47 is widely expressed in most urothelial carcinoma cells, and CD44+ CSCs have higher CD47 expression level compared to subset of CD44−tumor cells." (PMID 35903544, 2022). "Basal cell markers like basal cytokeratins and CD44 are detected in the basal type urothelial carcinoma and markers of the luminal umbrella cells like cytokeratin 20 or uroplakin are found in the luminal type of urothelial carcinoma." (PMID 26316886, 2015). "Nevertheless, there is no data showing the expression of CD44 or SOX2 mediates the tumor progression in dog urothelial carcinoma." (PMID 32523078, 2020). "Basal urothelial carcinoma shows a positive stain for CD44 and CK5/6, and a negative stain for CK20 and pPARγ, whereas luminal urothelial carcinoma shows an opposite pattern." (PMID 35805028, 2022).
clear cell renal cell carcinoma (12 papers, 2014 to 2025). "The expression of CD44 in clear cell renal cell carcinoma (ccRCC) correlates with tumor grade and patient survival, influenced by the methylation of genes." (PMID 40558504, 2025). "Through regulation by ribosomal S6 kinase 4 (RSK4), a downstream factor of the RAS/MEK/ERK signalling pathway, CD44 and MMP-9 overexpression is highly associated with the invasion and metastasis grade of metastatic clear cell renal cell carcinoma." (PMID 34944493, 2021). "In vitro studies on MIF/CD74 (CD44) knockdown by siRNA approach, as reported for clear cell renal carcinoma, shed light on this aspect." (PMID 24939415, 2014). "However, our knowledge of the biological function and mechanism of CD44 in clear cell renal cell carcinoma (ccRCC) is limited." (PMID 37509716, 2023). "Expressions of CRAs, CD44, DPP4, GOT1 and HMGCR were significantly increased in renal clear cell carcinoma compared with those in normal kidney tissue." (PMID 33996565, 2021).
glomerulosclerosis (12 papers, 2010 to 2025). A hardening of the kidney glomerulus caused by scarring of the blood vessels. "CD44+ expression in MC was associated with hematuria and % of glomerulosclerosis, and CD44 interstitial expression was associated with the tubule-interstitial fibrosis (TIF) score." (PMID 37108355, 2023). "In aged CD44 wild-type mice, heightened CD44 expression triggers phenotypic shifts in parietal epithelial cells, leading to glomerular hypertrophy, reduced podocyte density and glomerular sclerosis." (PMID 39050866, 2024). "In genetically labeled PEC reporter mice with FSGS, the migration of PECs towards the injured glomerular tuft was noted, and the intensity of CD44 expression by PECs was positively related to the severity of glomerulosclerosis." (PMID 36830635, 2023). "In the present study, CD44 expressions were upregulated in both T and B lymphocytes, suggesting that glomerular parenchymal cells, together with lymphocytes, participate in glomerulosclerosis." (PMID 34222276, 2021). "In this study, however, the female aged CD44+/+ mice had more glomerulosclerosis than the male CD44−/− mice." (PMID 32597007, 2020). "For example, CD44, a marker of activated parietal epithelial cells, may reflect the processes of glomerulosclerosis in MN or IgAN but, at the same time, may also be an essential feature for differentiating FSGS from MCD." (PMID 34830001, 2021). "CD44 reflects the activation of parietal epithelial cells, which triggers glomerulosclerosis." (PMID 34830001, 2021). "However, following the seminal observation that PECs begin to express CD44 in certain glomerular diseases, new light has been shed on their role in glomerulosclerosis." (PMID 32597007, 2020). "Moreover, increased CD44 in glomerular parietal epithelial cells in aged mice contributed to glomerular hypertrophy and lower podocyte density, accompanied by segmental and global glomerulosclerosis." (PMID 41301516, 2025). "The current thinking around glomerulosclerosis, a hallmark of kidney aging, is evolving from the original podocyte‐centric view, to one that also includes the activated glomerular parietal epithelial cell (PEC), often defined as de novo expression of CD44, and increased pERK." (PMID 32597007, 2020). "For example, CD44-positive cells activate parietal epithelial cells (PEC), which is one of the key factors in the development of glomerulosclerosis in patients with chronic glomerulopathies." (PMID 37108355, 2023). "In an experimental study, PECs of CD44+/+ in mice produce vimentin and α-SMA, that are accompanied by segmental and global glomerulosclerosis." (PMID 37108355, 2023). "Many studies focused on the role of aPECs (CD44+/Ki67+) in the genesis of sclerotic lesions, while less information is available regarding the role of PECs in the mechanism of protein uptake in normal kidney and in proteinuric nephropathies, a key step that may eventually lead to glomerulosclerosis." (PMID 37594671, 2023). "The absence of CD44 in aged null mice was accompanied by reduced glomerulosclerosis, glomerular hypertrophy, mTOR activation, and PEC activation, supporting a probable role for CD44 in kidney aging." (PMID 32597007, 2020). "Not only were CD44-positive PEC observed in higher numbers in iPec-Cd9wt/wt DOCA mice, but the number of CD44 + PEC also strongly correlated with the number of abnormal glomeruli (R = 0.89) and glomerulosclerosis (R = 0.90)." (PMID 31341160, 2019). "Taken together, one might speculate that the absence of any increase in CD44 in aged mice limits glomerulosclerosis through several mechanisms: reduced PEC activation, reduced changes from the epithelial phenotype, and reduced glomerular hypertrophy." (PMID 32597007, 2020).
glomerulosclerosis (continued). "In summary, we demonstrated that in CD44−/− mice, the lack of functional CD44, limited age‐related increases in segmental and global glomerulosclerosis, glomerular hypertrophy, an increase in Bowman's capsule length, changes in the PEC phenotype, PEC ERK activation, and mTOR activation." (PMID 32597007, 2020).
influenza (12 papers, 2008 to 2025). An acute viral infection of the respiratory tract, occurring in isolated cases, in epidemics, or in pandemics; it is caused by serologically different strains of viruses (influenzaviruses) designated A, B, and C, has a 3-day incubation period, and usually lasts for 3 to 10 days. "As the CD4+ T cell-specific immunodominant LCMVgp61-80 epitope contains a cryptic epitope recognized by CD8+ T cells, we analyzed CD8+CD44+ T cells at 8 and 42 days after influenza challenge for IFNγ expression following LCMVgp61-80 peptide restimulation." (PMID 39283916, 2024). "Staining at d10 showed that smoke exposure before influenza caused a large increase in virus specific CD8+ T cells in BALF, most of which were positive for CD44." (PMID 18627612, 2008). "Compared with those who did not receive the influenza vaccine, women who received the influenza vaccine had greater numbers of genes encoding T-cell surface markers (CD44, CD8A, CD62L and CD25) in breast milk." (PMID 39294774, 2024). "The origins and the differential functions of eosinophils with a phenotype characterized as CD69/CD125/CD63high and CD44/CCR3low could be subjects of further investigations, particularly in other viral respiratory diseases, such as influenza or respiratory syncytial virus infection." (PMID 40710346, 2025). "For this, we analyzed TFH (CD4+CD44+CXCR5+PD-1+) cells compared to Teff (CD4+CD44+CXCR5−PD-1−) cells following LCMV, influenza, T. muris, H. polygyrus and C. rodentium infection." (PMID 40926076, 2025). "Congruently, in a murine influenza model, NK1.1- DN T cells localized in the lung parenchyma, exhibited a pre-activated TRM phenotype (CD44+CD69+CD103+), and expanded robustly after infection, underscoring the capacity of DN TRM to participate in acute, site-restricted immunity." (PMID 41164185, 2025). "Influenza alone mice had slightly more CD4+ CD44+ and CD8+ CD44+ cells than no treatment mice in BALF, especially with smoke exposure." (PMID 18627612, 2008). "In addition, it could be shown, that CD44 enhanced the survival of memory Th1 cells since Cd44-KO mice could not build memory in an influenza model." (PMID 26172046, 2015).
mesothelioma (12 papers, 2007 to 2024). A usually malignant and aggressive neoplasm of the mesothelium which is often associated with exposure to asbestos. "Silencing of Fra-1, a component of the dimeric transcription factor, activator protein-1 (AP-1), inhibits mRNA expression of c-met and cd44 in rat mesothelioma cells and is causally linked to maintenance of the transformed phenotype." (PMID 18096084, 2007). "We previously reported that increases in Fra-1 expression in rat mesotheliomas were causally linked to genes governing cell motility and invasion (cd44 and met)." (PMID 18096084, 2007). "Inhibitors such as exemestane, trametinib and statin exert profound antiproliferative effects on mesothelioma growth either by a direct downregulation of CD44 or the suppression of CD44 and its associated signaling pathways attesting the critical role of CD44 in modulating tumor growth in MPM." (PMID 28403901, 2017). "An increase in CD44 expression was detected in cells involved in the early stages of mesothelioma (tumor initiating cells, TICs)." (PMID 39451527, 2024). "The interaction of CD44 with its ligand HA has revealed an important role in modulating cell proliferation and invasiveness in mesothelioma." (PMID 39451527, 2024). "CD44 is known as a receptor for hyaluronic acid, which is a biomarker of asbestos-induced mesothelioma in pleural effusion." (PMID 29419731, 2018). "Exemestane, a drug that acts by reduction of CD44, inhibits proliferation and migration in mesothelioma cells." (PMID 26078352, 2015). "Here we present evidence that Fra-1 activation is through multiple survival pathways and that its expression governs human mesothelioma cell migration partially via indirect modulation of CD44 expression." (PMID 18096084, 2007). "In consideration of this, CD44 has been evaluated as potential biomarker for mesothelioma." (PMID 39451527, 2024). "Subsequent experiments aimed to provide a proof of principle that pharmacological inhibition of OPN signaling, by targeting the receptor CD44, could indeed decrease mesothelioma cell growth in vivo." (PMID 37398648, 2023). "Additionally, CD44 interacts with osteopontin, which is another biomarker of mesothelioma, certain collagens, and MMPs." (PMID 29419731, 2018). "Furthermore, the use of a monoclonal antibody against CD44 inhibits proliferation by 12–40% and migration by 10–35% in mesothelioma cell lines." (PMID 26078352, 2015). "However, combination treatment of ALDHhigh/CD44+ subpopulations isolated from three mesothelioma cell lines (H28, H2052 and Meso4) using the ALDH1 inhibitor, diethylaminobenzaldehyde (DEAB), induced cisplatin sensitivity in these cells and significantly reduced cell viability." (PMID 33550205, 2021). "Microarray (Affymetrix) data comparing rat pleural mesothelial cells (with and without exposure to crocidolite asbestos) and rat mesotheliomas indicate that CD44 was increased in mesotheliomas and in mesothelial cells after acute exposure to asbestos." (PMID 26078352, 2015). "The combined use of CD44 and ALDH widens the window for identification and targeting of a drug-resistant population which may improve the current treatment modalities in mesothelioma." (PMID 24884875, 2014). "Notably, it was found that silencing of CD44 significantly abrogated the HA-mediated cellular effects in the 2 MPM cell lines indicating the essential role of CD44/HA binding in modulating migration and proliferation of mesothelioma cells." (PMID 28403901, 2017). "These authors further observed that HAS2-transfected cells demonstrated a two-fold increase in the expression of the HA receptor, CD44 accompanied by increased cell motility, thus, disclosing the critical role of HA in the dissemination of mesothelioma cells in adjacent nontumor tissues." (PMID 28403901, 2017).
mesothelioma (continued). "Mesothelioma stem cells (MSCs) might be responsible for tumor repopulation after chemoradiation in murine mesothelioma, and cisplatin-resistant, CSC-like subpopulations could be enriched by aldehyde dehydrogenase (ALDH)high and CD44+ in mesothelioma cell lines." (PMID 33072611, 2020).
metastasis (12 papers, 2013 to 2025). The spread or migration of cancer cells from one part of the body (where they first appeared) to another. "PARD6G-AS1 hypomethylation and CD44 overexpression showed significant association with advanced FIGO stage and positive lymph node metastasis." (PMID 40357366, 2025). "In other words, CD44 rs187115 polymorphism was associated with TNM stage, tumor size and lymph node metastasis in CRC." (PMID 31682231, 2019). "In bone metastasis cell lines, it had been reported that CD44 cell acts as the CSC and promotes bone metastases by enhancing tumorigenicity, cell motility, and HA production." (PMID 30858465, 2019).